RSBN1 (round spermatid basic protein 1)
Description:
Histone demethylase that specifically demethylates dimethylated 'Lys-20' of histone H4 (H4K20me2) and trimethylated 'Lys-20' of histone H4 (H4K20me3) into monomethyl H4K20 (H4K20me1) thereby modulating chromosome architecture. May play a critical role in regulating H4K20 methylation during spermatogenesis.
Synonyms: KDM9; FLJ11220; ROSBIN
Tractability: PROTAC: UniProt records ubiquitination sites on it; ubiquitination databases record sites on it; its protein half-life has been measured.
Gene: Protein-coding gene on chromosome 1 (113,761,832 to 113,812,476, reverse strand). Ensembl gene ENSG00000081019.
Subcellular location: Nucleus; Cytoplasm, perinuclear region
Subcellular location (Human Protein Atlas): Nucleoplasm
Gene Ontology:
Molecular function: protein binding; histone H4K20 demethylase activity
Biological process: spermatogenesis; chromatin remodeling
Cellular component: nucleus; perinuclear region of cytoplasm
Genetic constraint (gnomAD): Loss-of-function variants: 22 observed, 62.02 expected, observed/expected ratio (o/e) 0.35, 90% interval 0.25 to 0.51. The upper end of that interval is the gene's LOEUF score, 0.51, which puts it in group 2 of 6, group 1 being the genes least tolerant of losing a copy. Missense variants: 784 observed, 967.75 expected, observed/expected ratio (o/e) 0.81, 90% interval 0.76 to 0.86. Synonymous variants: 395 observed, 361.86 expected, observed/expected ratio (o/e) 1.09, 90% interval 1 to 1.19.
Homologues: Orthologues: chimpanzee RSBN1 (99% identical), macaque RSBN1 (99% identical), rabbit RSBN1 (96% identical), pig RSBN1 (96% identical), rat Rsbn1 (94% identical), mouse Rsbn1 (94% identical), guinea pig RSBN1 (94% identical), dog RSBN1 (92% identical), zebrafish RSBN1 (51% identical), Drosophila melanogaster CG10600 (32% identical), Caenorhabditis elegans dpy-21 (28% identical). Paralogues in human: RSBN1L (47% identical).
Diseases named in the same sentence as RSBN1 in open-access papers:
RSBN1 is named in the same sentence as 13 diseases in open-access papers, as found by Europe PMC text mining. Sharing a sentence is not in itself a finding about the gene and the disease. The quoted sentences say what the papers report.
breast carcinoma (2 papers, 2017 to 2018). "Besides, in luminal breast cancer, RSBN1 high expression is associated with a better prognosis in luminal breast cancer." (PMID 29854292, 2018). "In breast cancer lineages RSBN1 expression is induced by hypoxia and the gene is a potential HIF target." (PMID 29854292, 2018). "In other words, expression of RSBN1 in murine female breast tissues was not investigated, and it may well be regulated by HIF as all seven lists include it, it may be expressed in breast tissues, and may have a role in response to hypoxia in breast cancer consequently." (PMID 28619028, 2017).
rheumatic diseases (1 paper, 2024). "We would like to highlight that the variant rs6679677, which was significantly associated with T1DM, is situated between PHTF1 (Putative Homeodomain Transcription Factor 1) and RSBN1, which are implicated in systemic seropositive rheumatic diseases." (PMID 38256693, 2024).
cancer (2 papers, 2017 to 2018). A tumor composed of atypical neoplastic, often pleomorphic cells that invade other tissues. "Other cancer causing candidates were SMURF2, PIK3AP1, RSBN1, TTN and SEMA6D, which were ranked in the top 25% potential drivers in transposon insertional mutagenesis studies in mice." (PMID 29854292, 2018). "Likewise, we found a number of genes whose expression follows this pattern: late-stage cancers < early-stage cancers < normal tissue, such as ADHFE1, LOC653501, NT5DC1, RSBN1, SOCS2 and TAPT1 in five cancer types." (PMID 28427185, 2017).
infection (1 paper, 2020). The state of being infected such as from the introduction of a foreign agent such as serum, vaccine, antigenic substance or organism. "Upon infection, DC displayed the down-regulation of a gene related to the DNA repair and mitotic cell cycle, INTS3, and the up-regulation of RSBN1, a gene involved in chromatin organization." (PMID 33365028, 2020).
RSBN1 also shares sentences with these, for which no sentence is quoted: Obesity (2 papers); schizophrenia (2); anorexia nervosa (1); autoimmune disease (1); bipolar disorder (1); depression (1); diabetes (1); rheumatoid arthritis (1); tumor (1).